IL10 (interleukin 10)
Diseases named in the same sentence as IL10 in open-access papers (continued):
Sharing a sentence is not in itself a finding about the gene and the disease.
atherosclerosis (continued). "First, due to enhanced expression of PU.1, KLF4, MafB, and LXRα, these cells acquired antiinflammatory properties, including the increased secretion of IL-10, IL-1RA, and IL-5, aiding to resolve inflammation and protect against atherosclerosis." (PMID 39531328, 2024). "In a study, the substitution of miR-122 with miR-155 in inflammatory atherosclerosis led to the activation of IL-10 mRNA, thus triggering the inflammatory response." (PMID 38558788, 2024). "This study demonstrated EV-based delivery of IL-10 mRNA for treatment of atherosclerosis, providing a foundation for developing other EV-based mRNA delivery platforms to treat inflammatory diseases." (PMID 38505610, 2024). "Anti-inflammatory cytokines released by Tregs, such as TGF-β, IL-10, and IL-35, not only enhance plaque stability but are also key in inhibiting atherosclerosis." (PMID 38558816, 2024). "In contrast, M2 macrophages contribute to atherosclerosis by secreting anti-inflammatory factors (such as IL-10 and TGF-β), promoting fibrosis and plaque stabilization, thereby reducing inflammation and facilitating tissue repair." (PMID 39726810, 2024). "IL-10 has been shown to have anti-inflammatory properties, which decelerate the progression of atherosclerosis by inhibiting inflammation and cell apoptosis." (PMID 39062180, 2024). "There is evidence that interleukin-10 (IL-10) exerts diverse antiatherogenic effects throughout different stages of atherosclerosis and in the thrombus formation." (PMID 38851847, 2024). "IL-10 was found to have potent anti-atherosclerotic effects, which was demonstrated by a 60% reduction in fatty lesions in diet-induced atherosclerosis in IL-10 knockout mice upon in vivo supplementation of IL-10." (PMID 38675778, 2024). "It was found there that administration of physiological amounts of KYNA to the mice deficient in IDO limits the expression of the major immunoregulatory atheroprotective cytokine IL-10 and accelerates atherosclerosis progression." (PMID 39000041, 2024). "Tregs are considered beneficial in CHD due to their production of transforming growth factor and IL10; adoptive transfer of Tregs has been demonstrated to minimize atherosclerosis, while depletion of Tregs increases atherosclerosis." (PMID 37928762, 2023). "In a mouse model, an inverse relationship was shown between the severity of atherosclerosis and IL-10 production by B cells, and it was also found that high cholesterol levels can mask the revealed atheroprotective properties of IL-10 + B-lymphocytes." (PMID 36831189, 2023). "IL-10 is an anti-inflammatory cytokine with deactivating properties in macrophage modulation and protects against atherosclerosis." (PMID 37286582, 2023). "The serum IL-1β, IL-6, and TNF-α levels were significantly reduced, whereas IL-10 was greatly increased in mice with early and advanced atherosclerosis after GLSP treatment." (PMID 36923537, 2023). "Elevated levels of IL-10 and IL-17 can inhibit the progression of atherosclerosis and significantly reduce atherosclerotic plaque, while deficiency can accelerate atherosclerotic plaque formation and atherosclerotic plaque instability." (PMID 37210474, 2023). "Exosome‐based engineered IL‐10 mRNA offers an efficient drug delivery vector target to macrophages in plaques of experimental atherosclerosis and alleviates atherosclerosis in ApoE−/− mice." (PMID 37206219, 2023). "The therapeutic effects on atherosclerosis have also been evaluated by using inflammation-responsive IL-10 mRNA-loaded exosomes." (PMID 37631256, 2023). "Regarding its role in atherosclerosis, data from in vitro and in vivo studies support that IL-10 prevents the progression of atherosclerotic plaque and reduces plaque instability and injury caused by reperfusion." (PMID 37629526, 2023).
atherosclerosis (continued). "Th2 cells secrete IL-5, IL-10, and IL-13 and activate B cells to produce antibodies, which are believed to counteract the pro-atherosclerosis effects of Th1 cells." (PMID 38143759, 2023). "Another cytokine playing an anti-inflammatory role in atherosclerosis is IL-10, which is primarily produced by macrophages and T and B lymphocytes and in very small quantities by brain capillary endothelial cells." (PMID 36882782, 2023). "The anti-inflammatory cytokines that were upregulated in AAA at 7, 14, and 28 days include IL-6, Il-2, IL-11, and IL-10; however, the anti-inflammatory cytokines that were upregulated in atherosclerosis include IL-6 and IL-2." (PMID 38327764, 2023). "Further evidence suggests that Tregs promote the transformation from pro-inflammatory M1 macrophages to anti-inflammatory M2 macrophages by releasing IL-10 to prevent atherosclerosis occurrence." (PMID 35509837, 2022). "In another study, anti-inflammatory IL-10 was targeted at atherosclerosis plaque using liposomes in conjugation with cRGD." (PMID 35455438, 2022). "Interleukin-5 (IL-5) and interleukin-10 (IL-10) were thought to be protective factors against atherosclerosis." (PMID 35651907, 2022). "Although the concept that IL-10 executes an anti-inflammatory role is accepted, the relationship between IL-10 and atherosclerosis is still unclear, thus limiting the application of IL-10-based therapies for this disease." (PMID 36110841, 2022). "Moving to IL-10 targeting, several studies have assessed the therapeutic value of its overexpression towards atherosclerosis." (PMID 36555579, 2022). "Further, miR-19b inhibits leukocyte activation by reducing interleukin 10 expression, and the lowered expression of this miRNA was observed in B cells of atherosclerosis patients." (PMID 35329950, 2022). "Given that Syrian golden hamsters possess metabolic features similar to humans, we generated an IL-10-deficient hamster model using CRISPR/Cas9 editing to investigate the role of IL-10 in lipid metabolism and atherosclerosis." (PMID 36110841, 2022). "Using a similar strategy, the same group also constructed inflammation-responsive Il-10 mRNA by replacing miR-122 with miR-155 enriched in the inflammatory sites of atherosclerosis." (PMID 36559192, 2022). "Our results provide insight into the relationship between IL-10 and atherosclerosis and have potential therapeutic implications for the treatment of atherosclerosis." (PMID 36110841, 2022). "Other than preclinical studies indicating a role in atherosclerosis, Treg cells and IL-10 were found in lesser concentrations in patients with a prior myocardial infarction." (PMID 36555579, 2022). "Atherosclerosis and the build-up of fatty streak and plaques are accelerated by aberrant levels of IL-6 and IL-10." (PMID 36139806, 2022). "IL-10 protein was then retained in the plaque and acted accordingly to attenuate atherosclerosis progression." (PMID 36555579, 2022). "IL-10 is an anti-inflammatory cytokine that leads to cardiovascular protection in human atherosclerosis, acute coronary syndrome, unstable angina, and heart failure." (PMID 36297479, 2022). "Inhibition of IL-1β reduced the sizes of formed atherosclerotic plaques and increased plasma IL-10 levels, thereby slowing the onset of atherosclerosis." (PMID 36211578, 2022). "On the other hand, IL-10 is considered an anti-inflammatory cytokine and was found to favorably influence the progression of atherosclerosis." (PMID 35928361, 2022). "This trend was complementary to plasma IL-6 and IL-10 levels, supporting the relationship between cytokines and atherosclerosis progression." (PMID 36139806, 2022). "It is roughly understood that inflammation linked with the hyperactivation of cytokines, such as IL-1β, IL-6, IL-10, and TNF-α causes pathogenesis of coronary heart disease and atherosclerosis." (PMID 36289895, 2022).
atherosclerosis (continued). "IL-10 is important as it protects against atherosclerosis by regulating atherogenic macrophage function and can mitigate atherosclerosis." (PMID 35203642, 2022). "The reduction in atherosclerosis correlated with immunoregulatory changes including increases in interleukin-10, expansion of Foxp3+ regulatory T cells, and inhibition of NF-kBp65 activation." (PMID 36290415, 2022). "IL-10 has a potential protective role in atherosclerosis and can be produced by macrophages and inhibits pro-inflammatory cytokine expression through a JAK/STAT3 dependent pathway." (PMID 34445361, 2021). "The clearance of ACs and the suppression of inflammation by IL-10 are required to prevent chronic inflammation and reduce atherosclerosis progression." (PMID 34957260, 2021). "The overexpression of IL-10 and its administration suppressed the disease development, implying the protective role of this cytokine in atherosclerosis." (PMID 33562334, 2021). "Of note, LIF, a pleiotropic cytokine, has been proven to be anti-inflammatory, and increases IL10 expression, which can ameliorate atherosclerosis." (PMID 33589571, 2021). "IL-10+-expressing B cells are decreased in human atherosclerosis and negatively correlate with the inflammatory markers in patients with CVD." (PMID 33572939, 2021). "The immune regulatory cytokine IL-10 is down-regulated in peripheral B cells in patients with atherosclerosis which was inversely correlated with the expression of miR-19a." (PMID 33988232, 2021). "Of note, ApoB100 plus IL-10-treated DCs ameliorated atherosclerosis, while IL-37tg mice-derived bone-marrow-derived DCs displayed reduced costimulatory molecules and MHC-II after administration of LPS." (PMID 34471467, 2021). "Tregs dampen immune responses by secretion of anti-inflammatory cytokines such as IL-10 and TGFβ as well as removal/sequestration of (co)stimulatory molecules and therefore, have been attributed a beneficial role in atherosclerosis." (PMID 33572939, 2021). "Treatment of Apoe−/− mice with this viral nucleoprotein markedly reduces atherosclerosis and induces a Tr1-type regulatory immune response characterized by enhanced IL-10 but reduced IFN-γ and IL-4 production." (PMID 33805071, 2021). "Since we observed increased plasma lipids, especially apoB containing lipoproteins, and decreased IL-10 in plasma, we next investigated the development of atherosclerosis in SLC37A2Δhema mice compared to controls." (PMID 34957260, 2021). "Cytokines produced by B cells can enhance immunomodulation during chronic inflammation; for example, TNF-α, IL-2, and IL-10 produced by B2 cells promoted atherosclerosis." (PMID 34522782, 2021). "Conventional B2 cells contribute to proatherogenic immune responses, while B1 cells or regulatory B cells protect against atherosclerosis by secreting natural IgM antibodies against oxidation-specific epitopes or IL-10, respectively." (PMID 34945203, 2021). "The release of TNF-α, IL-6, and IL-10 can activate NF-кB to promote the production of inflammatory factors such as IL-8, which further aggravates the inflammatory reaction in the atherosclerosis process." (PMID 34568579, 2021). "In a previous proof of concept report, we proposed a novel immunomodulatory strategy consisting in the local low-dose delivery of an IL-10-inducing formulation (containing VitD/Dexa) as a form of immune intervention for atherosclerosis." (PMID 34305950, 2021). "Direct immunization with ApoB-100 and ApoB-100 peptides protects from atherosclerosis, likely by the induction of IL-10 secreting protective Tregs." (PMID 33669769, 2021). "Blocking IL-10 accelerates atherosclerosis, whereas targeting the delivery of IL-10 via nanoparticles attenuates atherosclerosis." (PMID 34957260, 2021). "In our study, the mRNA levels of TNF-α and IFN-γ were abundantly expressed in the atherosclerotic lesions of the aorta in atherosclerosis mice, while the levels of IL-10 were the opposite." (PMID 34566648, 2021).
atherosclerosis (continued). "Conversely, in vivo supplementation with purified spleen CD4+CD25+ Tregs or IL-10-producing Tr1-like Tregs reduced atherosclerosis in Apoe−/− mice and induced a more stable plaque phenotype." (PMID 33805071, 2021). "Serum levels of IL-10 in patients with unstable angina were significantly lower than those with chronic stable angina, suggesting that IL-10 has a protective role in atherosclerosis." (PMID 34336007, 2021). "IL-10 is an anti-inflammatory cytokine known to decrease atherosclerosis when expressed by leukocytes." (PMID 33572939, 2021). "Of these, Hp2-2 has a higher Hb binding affinity than Hp1-1 and has an increased proinflammatory effect by increasing IL-10 secretion, leading to the destabilization of plaque during atherosclerosis development." (PMID 34445740, 2021). "Taken together, IL-10 is uniformly anti-inflammatory in the context of atherosclerosis, the intestine, or the oral cavity." (PMID 33562334, 2021). "IL-10 is a known anti-inflammatory factor that can prevent the occurrence and progression of atherosclerosis." (PMID 34744722, 2021). "Considering the antiatherogenic profile of IL-10, the presence of this cytokine in low-concentrations is considered to be a favourable condition for the progression of atherosclerosis and can be even referred to as a proatherogenic factor." (PMID 34771080, 2021). "The contemporary theory of the inflammatory-immunological pathomechanism of atherosclerosis includes the participation of interleukin-1β (Il), Il-6, Il-10, Il-12, RANTES, and homocysteine in this process." (PMID 34771080, 2021). "Another suggested mechanism by which IDO-1 protects against atherosclerosis is through inhibition of IL-10 production by a kynurenic acid (KA)-induced mechanism." (PMID 33117340, 2020). "According to the results of the CytoHubba analysis, we unexpectedly identified IL10 as a common hub gene in atherosclerosis, myocarditis, and myocardial ischemia." (PMID 32612856, 2020). "IL-35 is induced by proinflammatory stimulation and the early development of atherosclerosis and can inhibit endothelial cell activation, while IL-37 and IL-10 also play immunosuppressive roles as anti-inflammatory factors." (PMID 32733941, 2020). "According to numerous studies on atherosclerosis, lung diseases, and on tumors, we conclude that IL-10, TGF-β, and IFN-γ contribute to the resolution of inflammation, and that CSF enhances tissue repair." (PMID 32346605, 2020). "IL-10 is an important immunomodulatory cytokine that has been suggested to ameliorate cardiovascular diseases such as atherosclerosis." (PMID 32708790, 2020). "IL-10 is an inhibitory cytokine produced by activated lymphocytes and monocytes, thought to be protective against the development and progression of atherosclerosis." (PMID 33193911, 2020). "The human IL-10 gene transfer decreased atherosclerosis and played an important protective role in atherosclerotic plaque stability." (PMID 33029103, 2020). "Through the secretion of anti-inflammatory cytokines such as TGF-b, IL-10, and IL-35, they prevent further progression of atherosclerosis and postinfarction inflammation." (PMID 32104149, 2020). "Recent studies have shown that epigenetic regulation of IL-10 expression can influence the progression of diseases such as Behçet's's disease and atherosclerosis." (PMID 32582189, 2020). "Tregs can promote the transformation of pro-inflammatory M1 macrophages to fibrotic M2 macrophages by releasing IL-10, which helps to prevent atherosclerosis." (PMID 33585580, 2020).
atherosclerosis (continued). "Of note, several publications reported that DCs treated with IL-10 and ApoB100 ameliorate atherosclerosis, while IL-37tg mice-derived BMDCs and splenic DCs showed reduced expression of costimulatory molecules and MHC-II after treatment with LPS." (PMID 31686988, 2019). "Bregs exert immunosuppressive functions by secreting the cytokines IL-10 and TGFβ, and IL-10 disruption promotes inflammatory cell infiltration and cytokine generation and enhances atherosclerosis in mice." (PMID 31653058, 2019). "The present study investigated the involvement of Chlamydia trachomatis and Chlamydia pneumoniae infections and immunological markers (C-reactive protein, CRP, TNF-α, IL-6, IL-8, and IL-10) in the process of atherosclerosis." (PMID 30804931, 2019). "IL-10 plays a protective role in atherosclerosis by inhibiting Th1 differentiation and decreasing T cell and macrophage accumulation and by diminishing the production of proinflammatory cytokines." (PMID 31653058, 2019). "Many inflammatory pathways were enriched, such as atherosclerosis signaling, IL‐10 signaling, Th1 and Th2 pathways, and T‐cell receptor signaling." (PMID 29941542, 2018). "STAT3 activation also leads to increased gene expression of interleukin-10 (IL-10), the product of which is typically elevated in atherosclerosis." (PMID 30279971, 2018). "Pg-immunized mice with extensive atherosclerosis had lower IL-5, IL-10 and IL-22 levels than those with less atherosclerosis." (PMID 29329335, 2018). "While CCR5 showed a protective role in atherosclerosis by a mechanism involving interleukin-10, CCR1 supported inflammation and neointima formation after vascular injury." (PMID 30006564, 2018). "Third, replenishment of Apoe−/−/Baffr−/− mice with Il-10−/− B cells broke the resistance to atherosclerosis observed in AngII-infused Apoe−/−/Baffr−/− mice replenished with Il-10+/+ B cells." (PMID 28646220, 2017). "In order to assess the role of IL-10 in IL-37–mediated protection from atherosclerosis, we administered IL-37 or PBS together with anti-IL-10R mAb or isotype antibody." (PMID 28607385, 2017). "Finally, AngII induced IL-10 production by B cells was significantly attenuated by Agtr1a deficiency, and transfer of Apoe−/−/Baffr−/− mice with Agtr1a−/− B cells in the presence of AngII led to increased atherosclerosis compared with the transfer of Agtr1a+/+ B cells." (PMID 28646220, 2017). "Using a diabetic model, we found that recombinant human IL-37 attenuated both atherosclerosis and vascular calcification via regulating the production of osteoprotegerin and inflammatory cytokines such as IL-10, IL-18, TNF-α and IFN-γ17." (PMID 28607385, 2017). "Interleukin 10 is a kind of an anti-inflammatory cytokine which can reduce the formation of atherosclerosis and maintain the stability of atheromatous plaques, which play an important role in inhibiting the occurrence of ACS." (PMID 28224128, 2017). "Conversely, regulatory T (Treg) cells are proposed to be protective in atherosclerosis because they produce anti-inflammatory cytokines such as IL-10 and TGFβ and suppress immune responses through direct and indirect mechanisms." (PMID 28066329, 2016). "Although anti-inflammatory IL-10 was traditionally considered protective against atherosclerosis, a prospective study found that circulating IL-10 concentrations at baseline were positively associated with nonfatal myocardial infarction, stroke, or CVD death." (PMID 27527152, 2016). "As many of the ATLO B-1 cells express markers of immunosuppressive B regulatory cells (TGFβ1, IL-10, PD-L1, and FasL), it is conceivable that the majority of B-1 cells have anti-atherosclerosis impacts on the disease." (PMID 27777573, 2016).